FBXO42 (F-box protein 42)
Description:
Substrate-recognition component of some SCF (SKP1-CUL1-F-box protein)-type E3 ubiquitin ligase complex.
Synonyms: FBX42; JFK; KIAA1332
Tractability: PROTAC: ubiquitination databases record sites on it; its protein half-life has been measured.
Gene: Protein-coding gene on chromosome 1 (16,246,840 to 16,352,487, reverse strand). Ensembl gene ENSG00000037637.
Subcellular location (Human Protein Atlas): Nucleoplasm
Gene Ontology:
Molecular function: protein binding; ubiquitin-like ligase-substrate adaptor activity
Biological process: SCF-dependent proteasomal ubiquitin-dependent protein catabolic process
Cellular component: nucleus; SCF ubiquitin ligase complex
Genetic constraint (gnomAD): Loss-of-function variants: 11 observed, 67.31 expected, observed/expected ratio (o/e) 0.16, 90% interval 0.1 to 0.27. The upper end of that interval is the gene's LOEUF score, 0.27, which puts it in group 1 of 6, group 1 being the genes least tolerant of losing a copy. Missense variants: 701 observed, 952.77 expected, observed/expected ratio (o/e) 0.74, 90% interval 0.69 to 0.78. Synonymous variants: 324 observed, 346.2 expected, observed/expected ratio (o/e) 0.94, 90% interval 0.85 to 1.03.
Homologues: Orthologues: chimpanzee FBXO42 (99% identical), macaque FBXO42 (99% identical), pig FBXO42 (98% identical), dog FBXO42 (97% identical), mouse Fbxo42 (95% identical), rabbit FBXO42 (95% identical), guinea pig FBXO42 (95% identical), rat Fbxo42 (86% identical), tropical clawed frog fbxo42 (78% identical), Drosophila melanogaster Fbxo42 (29% identical), zebrafish fbxo42 (26% identical). Paralogues in human: HCFC1 (23% identical), HCFC2 (16% identical), LZTR1 (14% identical), KLHDC4 (11% identical), RABEPK (11% identical), KLHDC2 (10% identical), KLHDC1 (9% identical), KLHDC10 (9% identical), KLHDC3 (9% identical), KLHDC9 (7% identical).
Diseases named in the same sentence as FBXO42 in open-access papers:
FBXO42 is named in the same sentence as 10 diseases in open-access papers, as found by Europe PMC text mining. Sharing a sentence is not in itself a finding about the gene and the disease. The quoted sentences say what the papers report.
melanoma (3 papers, 2020 to 2023). A malignant, usually aggressive tumor composed of atypical, neoplastic melanocytes. "FBXO42 (F-box protein 42) is an E3 ubiquitin ligase associated with trametinib resistance in NRAS-mutated melanoma cells." (PMID 38084101, 2023). "Using the CRISPR–Cas9-mediated genome-wide screen, the authors identified FBXO42 loss as a driver of trametinib (MEK inhibitor) resistance in NRAS-mutated melanoma." (PMID 33800394, 2021). "As part of the RING-type family and HECT family, the F-box E3 ligase family member FBXO42 was also recently described as involved in the resistance of melanoma to targeted therapies." (PMID 33800394, 2021). "Here, a whole‐genome CRISPR‐Cas9 screen identified FBXO42 ubiquitin ligase involvement in resistance to trametinib treatment in the context of NRAS‐mutant melanoma." (PMID 31549767, 2020). "Our whole‐genome CRISPR‐Cas9 knockout screen identified the target Kelch domain‐containing F‐Box protein 42 (FBXO42) as a factor involved in NRAS‐mutant melanoma‐acquired resistance to the MEK1/2 inhibitor trametinib." (PMID 31549767, 2020). "Our whole‐genome CRISPR‐Cas9 knockout (KO) screen in NRASQ61R melanoma cells revealed the Kelch domain‐containing F‐Box protein 42 (FBXO42), an E3 ubiquitin ligase, involvement in resistance toward trametinib treatment." (PMID 31549767, 2020). "RNA sequencing analysis of NRAS‐mutant melanoma patient‐derived cell lines identified FBXO42 to be differentially expressed between resistant and sensitive patients treated with MEK inhibitors." (PMID 31549767, 2020). "In an effort to better understand the mechanistic role of FBXO42 in NRAS‐mutant melanoma, we performed a structure–function analysis of FBXO42 when devoid of its functional domains on the activation of the ERK pathway as a readout." (PMID 31549767, 2020). "To determine whether FBXO42 KO indeed leads to resistance in NRAS‐mutant melanoma cells, we knocked out FBXO42 from NRAS mutant cell lines." (PMID 31549767, 2020). "Indeed, we observed an increase in the expression levels of both RAS‐GTP and pERK in FBXO42 KO samples treated and untreated with trametinib, compared to the control cells, suggesting that KO of FBXO42 in NRAS‐mutant melanoma cells leads to MAPK pathway activation." (PMID 31549767, 2020). "To further assess the involvement of the TAK1 signaling pathway in trametinib resistance in NRAS mutant FBXO42 KO melanoma cells, we combined trametinib with takinib, the potent and selective TAK1 inhibitor, and tested their inhibition of FBXO42 KO cell growth." (PMID 31549767, 2020).
glioma (2 papers, 2024 to 2026). A benign or malignant brain and spinal cord tumor that arises from glial cells (astrocytes, oligodendrocytes, ependymal cells). "FBXO42, an understudied member of this family, has recently emerged as a modulator of key cellular processes, including cell cycle progression, the DNA damage response, and glioma stem cell survival." (PMID 41484364, 2026).
liver cancer (1 paper, 2021). An epithelial or non-epithelial malignant neoplasm that arises from the liver. "Next, we sought to explore whether GASC1 loss-of-function correlates with elevated FBXO42 expression in HCC by analyzing TCGA liver cancer samples (442 patients) from the cBio database." (PMID 33692332, 2021).
oligodendroglioma (1 paper, 2024). A well-differentiated (WHO grade II), diffusely infiltrating neuroglial tumor, typically located in the cerebral hemispheres. "Both these blocks are negatively correlated with the group of genes GPBP1L1, LRRC41, CSDE1, FBXO42, and SFRS4, which are associated with the oligodendroglioma type." (PMID 38812741, 2024).
cancer (2 papers, 2020 to 2024). A tumor composed of atypical neoplastic, often pleomorphic cells that invade other tissues. "FBXO42 KO results in increased ERK activation, known to lead to proliferation and drug resistance in different types of cancer." (PMID 31549767, 2020).
tumor (1 paper, 2021). "The posttranslational regulation of ROCK2 mediated by GASC1/FBXO42 axis provides a delicate control of ROCK2 protein stability during HCC initiation and tumor growth." (PMID 33692332, 2021).
FBXO42 also shares sentences with these, for which no sentence is quoted: breast cancer (1 paper); leukemia (1); pancreatic cancer (1); Parkinson disease (1).